AR (androgen receptor)
Diseases named in the same sentence as AR in open-access papers (continued):
Sharing a sentence is not in itself a finding about the gene and the disease.
hepatocellular carcinoma (118 papers, 2009 to 2026). A malignant tumor that arises from hepatocytes. "Treatment with an AMPK agonist showed promising results in reversing the malignancy and progression of hepatoma cells expressing AR mutations." (PMID 38182647, 2024). "This comparative analysis reinforces the notion that AR mutations play a critical role in driving hepatocellular carcinoma and highlights their oncogenic potential and role in liver cancer development." (PMID 38182647, 2024). "Several mutations proximal to the activation function domain-1 in androgen receptor lead to its constitutive activation and drive the development of hepatocellular carcinoma." (PMID 38182647, 2024). "It has also been reported that AR activation is associated with carcinogenesis in human hepatocellular carcinoma and pancreatic cancer with enhanced IL-6 signaling." (PMID 31836734, 2019). "Marked up-regulation of aldose reductase (AR) is reportedly associated with the development of hepatocellular carcinoma (HCC)." (PMID 28978011, 2017). "Importantly, A7269662 demonstrated greater efficacy in inducing cytotoxicity in hepatoma cells expressing AR mutations compared to those expressing wild-type AR." (PMID 38182647, 2024). "Furthermore, we have observed that hepatoma cells expressing these AR mutations exhibit notable sensitivity to the AMPK activator A769662." (PMID 38182647, 2024). "Higher serum androgen levels and an androgen receptor (AR) gene containing shorter CAG repeats (which lead to higher AR activity) have been clinically linked to higher risks of hepatitis B virus (HBV)-mediated hepatocellular carcinoma (HCC)." (PMID 28957431, 2017). "This research found that among mammals and fishes, the microsatellite sequences are conserved in the genes of epidermal growth factor receptor, ataxia telangiectasia mutated and androgen receptor corresponding to cancers, ataxia telangiectasia and hepatocellular carcinoma, respectively." (PMID 25520927, 2014). "Sex hormone receptors such as estrogen receptors (ERα and ERβ), progesterone receptor (PR) and androgen receptor (AR) are members of the hormone receptor family and have been associated with several human cancers, including breast, ovarian, prostate, colon, pancreas and hepatocellular carcinoma." (PMID 40868070, 2025). "The androgen receptor (AR) plays an important role in male-dominant hepatocellular carcinoma, and specific acquired somatic mutations of AR have been observed in HCC patients." (PMID 38182647, 2024). "P-CREB functions as a downstream molecular mediator in AR-mediated glycolysis in hepatocellular carcinoma (HCC), and its silencing effectively abolishes AR-induced glycolysis, cell proliferation, and susceptibility to glycolysis inhibition." (PMID 38202657, 2023). "For example, the expression of circARSP91 in human hepatocellular carcinoma (HCC) is suppressed via upregulation of ADAR1 p110 caused by the androgen receptor (AR)." (PMID 32943996, 2020). "AR is implicated in the pathogenesis of hepatocellular carcinoma (HCC)." (PMID 40583627, 2025). "The high incidence of hepatocellular cancer in men is related to factors such as testosterone, dihydrotestosterone, androgen receptor and proteomic defects." (PMID 41199834, 2025). "RBMY genes have shown a role in hepatocellular carcinoma and is potentially involved in AR activity regulation." (PMID 40454088, 2025). "This research not only provided a rationale for AR proteins against hepatocellular carcinoma, but also offered a reference for future anti-tumor studies of protein analogues." (PMID 39215362, 2024). "To further investigate the role of AMPK in AR mutation-driven hepatocarcinogenesis, we suppressed the expression of PYGB and SREBP1, two key downstream targets of AR mutations, using siRNA in hepatoma cells." (PMID 38182647, 2024).
hepatocellular carcinoma (continued). "In contrast, androgen exposure variably upregulated AR mRNA transcription in the hepatocellular carcinoma cell line, genital skin fibroblasts, rodent prostate, rodent hippocampus and osteoblastic cell line." (PMID 39337689, 2024). "We observed that stable expression of AR WT promoted hepatoma cells growth and colony formation compared to the control vector." (PMID 38182647, 2024). "Of note, hepatitis B virus replication is enhanced by androgen and the androgen receptor in mice, and males are more likely to develop HBV-associated hepatocellular carcinoma." (PMID 38932117, 2024). "The AR is implicated in the development and pathogenesis of hepatocellular carcinomas (HCC)." (PMID 37626712, 2023). "The elevated CREB5 promoted cellular proliferation in hepatocellular carcinoma, cell invasion in ovarian cancer, and resistance to androgen-receptor antagonists in prostate cancer." (PMID 37816820, 2023). "Inverse correlation between AR and PD-L1 levels has been reported in muscle invasive or metastatic urothelial, thyroid and hepatocellular carcinomas, suggesting PD-L1 downregulation through the AR pathway." (PMID 37941543, 2023). "Interestingly enough a dual role for AR has been shown in the promotion of hepatocellular carcinoma (HCC) initiation; and loss of AR leads to HCC metastasis with increased incidence of undifferentiated tumors in preclinical models." (PMID 37091854, 2023). "The AR knock-out in induced the hepatocellular carcinoma cellular model showed delayed initiation of cancerogenesis, while on the other hand, tumor growth and metastasis were intensified later." (PMID 36359245, 2022). "In hepatocellular carcinoma, AR expression (at the mRNA level) is inhibited by HIF2-α, which is expressed in GBM cells exposed to chronic hypoxia." (PMID 36361793, 2022). "AR is an androgen receptor involved in the growth and progression of hepatocellular carcinoma, it can inhibit the expression of CD90 in circulating tumor cells by up-regulating histone 3H2A." (PMID 33628636, 2021). "Our results are consistent with other studies demonstrating that AR can bind directly to Nanog gene promotor and promote cancer cell stemness in hepatocellular carcinoma and ovarian cancer." (PMID 34094902, 2021). "In hepatocellular carcinoma, miR-135b-5p has been shown to suppress AR-mediated cell proliferation, through the regulation of HIF-2α/c-Myc/P27 axis." (PMID 34831421, 2021). "We found that STAT6 mediates two modules, while TFs such as JUN, AES, and AR mediate a module that affects the development and progression of hepatocellular carcinoma." (PMID 34651050, 2021). "Androgen receptor (AR) can suppress hepatocellular carcinoma (HCC) invasion and metastasis at an advanced stage." (PMID 33118329, 2020). "Androgen receptor appears to be expressed in subset of hepatocellular carcinomas (HCC), although, like pancreatic cancer, the incidence has not been well defined." (PMID 28085048, 2017). "AR has been shown to regulate cell migration by suppressing the nuclear factor kappa B/matrix metallopeptidase 9 pathway and further inhibiting hepatocellular carcinoma metastasis." (PMID 27023146, 2016). "Another study also found that mitochondrial dysfunction has high AR expression in hepatoma cells, leading to the facilitation of cell migration." (PMID 25825984, 2015). "Human liver carcinoma HepG2 cells had higher GO mRNA expression when AR was incorporated into the cells (P < .05), and, consequently, higher oxalate secretion was detected in the culture media of these cells (P < .01 for 48 and 72 hours)." (PMID 24956378, 2014). "Transcription of CDK20 (CCRK) was activated by ligand-bound androgen receptor (AR) in hepatocellular carcinoma cells (HCCs), and CDK20 in turn upregulated β-catenin signaling, which upregulated the expression of the β-catenin target gene, AR, creating a cycle that induced tumor growth." (PMID 39941813, 2025).
hepatocellular carcinoma (continued). "For instance, the androgen receptor could upregulate ADAR1 p110 to inhibit the production of circARSP91 in hepatocellular carcinoma and promote the growth of hepatocellular carcinoma." (PMID 39550559, 2024). "To investigate the role of the ARQ62L and ARE81Q mutations in hepatoma cells, we constructed stable expression of ARQ62L and ARE81Q respectively in HCC-LM3 and MHCC-97H cells and certified the overexpression level of AR mutations respectively on mRNA and protein levels." (PMID 38182647, 2024). "Indeed, increases in specifically oleic acid–containing (18:1) DAGs have been shown to drive protein kinase Cε–mediated hepatic insulin resistance in NAFLD and also stimulate the androgen receptor to drive obesity and NAFLD-associated hepatocellular cancer." (PMID 36749637, 2023). "In hepatocellular carcinoma AR downregulates PD-L1 acting as PD-L1 transcriptional repressor." (PMID 37941543, 2023). "The overexpression of AR results in the decreased expression of PD-L1, and the knockdown of AR by small hairpin RNA (shRNA) leads to the increased expression of PD-L1 in human hepatocellular carcinoma cells." (PMID 37373038, 2023). "miR-299-3p, another androgen receptor (AR) targeting miRNA, which showed downregulation in PCa from AA patients, has also been shown to function as a tumor suppressor in a number of cancers including colon cancer and hepatocellular carcinoma." (PMID 37190259, 2023). "Of them, AR has been demonstrated to negatively regulate PD-L1 expression, and therefore lower AR-expressed tumors achieved a better response to immunotherapy in hepatocellular carcinoma." (PMID 35557959, 2022). "Elevated AR was observed in hepatocellular carcinoma; however, its role is complex." (PMID 36359245, 2022). "Steroid sex hormones may induce the occurrence and development of hepatocellular carcinoma through relevant receptors in the liver; among these receptors, AR negatively correlated with the degree of liver injury." (PMID 36467100, 2022). "Furthermore, in hepatocellular carcinoma, ACh acting on androgen receptor endorses SNU-449 cell invasion and migration via activation of signal transducer and activator of transcription 3 (STAT3) and AKT signaling pathways." (PMID 36614038, 2022). "Previously, androgen receptor signaling has been shown to suppress programmed cell death ligand 1 (PD-L1) transcription in hepatocellular carcinoma (HCC) cells and may thus exert immune stimulatory effects." (PMID 36368318, 2022). "Furthermore, such low As3+ exposure (100–700 nM) using a hepatoma cell line has also been shown to inhibit transcription of androgen receptor signaling modulated target molecules, possibly by interaction with its zinc finger containing DNA binding domain." (PMID 34032870, 2021). "The androgen receptor (AR) is an enticing therapeutic target in hepatocellular carcinoma (HCC)." (PMID 33574348, 2021). "Intriguingly, it has been reported that AR signalling may modulate miR-146a-5p via binding to the androgen-response-elements 2 (ARE2) located on the promoter region of miR-146a-5p in hepatocellular carcinoma." (PMID 33317606, 2020). "Androgen receptor (AR) may play a key role in influencing the progression of hepatocellular carcinoma at different stages." (PMID 32963562, 2020). "The expression of androgen receptor (AR) has been detected in hepatocellular cancer (HCC)." (PMID 29312607, 2017). "In terms of AR specifically in biliary tract cancer, structural variants have been associated with a risk of gallbladder cancer, and AR signaling has been implicated in hepatocellular cancer development although there has not been a direct link with cholangiocarcinoma." (PMID 39300603, 2024). "Additionally, a separate study found that a structural derivative of emodin, emodin succinyl ester (ESE), inhibits malignant proliferation and migration of hepatocellular carcinoma by suppressing the interaction between androgen receptor (AR) and enhancer of zeste homolog 2 (EZH2)." (PMID 38892575, 2024).
hepatocellular carcinoma (continued). "Therefore, regulation of ROS generation and AR phosphorylation may be a new target for hepatoma therapy." (PMID 35721110, 2022). "Interestingly in a mouse model of diethylnitrosamine (a hepatotoxicant and hepatocarcinogen)-induced formation of hepatocellular carcinoma (HCC), this treatment was also associated with fibrosis and accumulation of AR positive mesenchymal cells and immune cells." (PMID 36551674, 2022). "PRPF6 is reported to be related with spliceosome in colon cancer and androgen receptor (AR) signaling in hepatocellular carcinoma (HCC)." (PMID 33584809, 2020). "The role of the Androgen Receptor (AR) expression and its activity in the prognosis of hepatocellular carcinoma (HCC) remains inconclusive." (PMID 33328560, 2020). "In hepatocellular carcinoma (HCC), the androgen receptor (AR) acts as a positive regulator of the CDK20 promoter." (PMID 39800748, 2025). "Similarly, in later years, it was demonstrated that in hepatocellular carcinoma (HCC), AChE activated the STAT3 and AKT pathways by interacting with the androgen receptor (AR), enhancing the migration and invasion of HCC cells while inhibiting their apoptosis." (PMID 40678419, 2025). "Among the different types of AR gene in our research, ARQ62L showed the highest carcinogenic or cancer-promoting activity in hepatoma cells, followed by ARE81Q, with AR WT exhibiting a lower level of activity." (PMID 38182647, 2024). "Importantly, a number of studies suggested that both HBV and HCV infections can promote androgen receptor (AR) signaling in hepatocellular carcinoma (HCC)." (PMID 35865814, 2022). "In the regulation of transcription factors, STAT6 essentially regulates two functional disorder modules, while TF such as AR and ATF2 has a driving effect on one module, which affects the occurrence and development of hepatocellular carcinoma." (PMID 34651050, 2021). "Based on our findings, we concluded that gene and protein expression levels of TSPY1 and AR tended to increase in hepatoma cells from non-metastatic or low-metastatic potential to high-metastatic potential." (PMID 36261201, 2022). "Using an in vitro model, we also show direct hepatic actions of a nonaromatizable AR agonist protecting hepatoma cells from lipid accumulation, in line with previous reports." (PMID 25550469, 2015). "Androgen receptor (AR) could directly target the circR7 host gene promoter to suppress circR7 formation, up‐regulate miR‐7‐5p, which might directly target the VE‐cadherin and Notch4 3′UTR to suppress VM formation in hepatocellular carcinoma." (PMID 39964093, 2025). "For instance, a negative correlation between AR and PD-L1 expression was reported in tumors from patients with hepatocellular carcinoma, and increased lymphocyte infiltration was observed in AR- negative tumors treated with anti-PD-L1 drugs compared to AR-positive tumors." (PMID 40612952, 2025). "AR upregulates integrin β1 expression through the PI3K/AKT/mTOR signal pathway, consequently, increasing in cellular adhesion, which could be a potential characteristic of advanced hepatocellular cancer with high metastasis." (PMID 38966543, 2024). "Cisplatin can suppress the androgen receptor (AR) expression by increasing miR-34a-5p to suppress AR expression, and the inhibited AR may function through upregulation of ULBP2 protein, thereby enhancing NK cell function and preventing hepatocellular carcinoma progression." (PMID 36313765, 2022). "The well-documented role of HBV in hepatocellular carcinoma (HCC) indicates that a virus–host feedback loop between the X gene of HBV and AR is established in HBV-infected male hepatocytes." (PMID 34803967, 2021). "CCRK connected AR and β-catenin/TCF signaling cascades and was responsible for anomalous activation of β-catenin in human hepatocellular carcinoma (HCC) which induced cell cycle progression and tumor formation in both xenograft and orthotopic models." (PMID 31027362, 2019).
hepatocellular carcinoma (continued). "The aim of the present study was to investigate the potential roles of the androgen receptor (AR) and matrix metalloproteinase (MMP)-2 and MMP-9 in hepatocellular carcinoma (HCC) tissues and whether their expression could be used as a predictor of the invasion and stage of cancer." (PMID 25667651, 2015). "However, the effects of AR-42 in hepatocellular carcinoma have not yet been studied." (PMID 26993777, 2016). "In humans or rodents, AR and aldo-keto reductase family 1B10 (AKR1B10, also known as AR-like-1), were often among the most significantly up-regulated genes in many types of cancers including cervical cancer, colon cancer, leukemia, pancreatic cancer and hepatocellular carcinoma (HCC)." (PMID 28978011, 2017).